GP1BA (glycoprotein Ib platelet subunit alpha)
Diseases named in the same sentence as GP1BA in open-access papers (continued):
Sharing a sentence is not in itself a finding about the gene and the disease.
lung squamous cell carcinoma (1 paper, 2025). "Currently, no study has directly shown a relationship between GP1BA protein level and lung squamous cell carcinoma risk." (PMID 41340014, 2025). "DMP1, GP1BA and HEPH remained associated with lung squamous cell carcinoma." (PMID 41340014, 2025).
migraine (1 paper, 2024). "We further found drugs targeted for another six proteins (CSK, FER, GP1BA, PLCG1, PLG, and SERPING1), although currently there are no indications for migraine." (PMID 38898596, 2024).
thyroid (1 paper, 2020). "However, four genetic variants associated with thyroid phenotypes published in the GWAS catalog (rs3761959, rs7528684, rs505922, and rs3184504) were also associated in cis and trans with nine circulating protein abundances (BGAT, CHSTB, DC-SIGN, Desmoglein-2, DYR, FCRL3, GP1BA, MBL, and VCAM-1)." (PMID 32182948, 2020).
vitiligo (1 paper, 2025). Generalized well circumscribed patches of leukoderma that are generally distributed over symmetric body locations and is due to autoimmune destruction of melanocytes. "Finally, we obtained ten matched genes (GP1BA, ANKS4B, CCDC87, CA8, HLA‐DOB, RHEBL1, NLRP7, GZMH, HERPUD1, and MAP2K1) as a vitiligo‐gene signature (VGS)." (PMID 40974370, 2025).
tumor (46 papers, 2010 to 2025). "Similar to Gp1ba−/− platelets, 10aa−/− platelets exhibited not only lower basal P‐selectin and PS levels but also lower tumor cell‐induced P‐selectin and PS exposure." (PMID 40491968, 2025). "GP1BA-driven platelet–tumor interactions characterize the CRC macroenvironment and likely promote local immunosuppression and metastatic dissemination." (PMID 40777024, 2025). "Notably, 10aa‐/‐ and Gp1ba‐/‐ platelets were in more resting states, reflected by the decreased surface expression levels of P‐selectin and PS, suggesting that the GPIbα cytoplasmic tail primes platelets to be activated by tumor cells." (PMID 40491968, 2025). "Except for EPO and GP1BA, the other 9 genes showed significant differences in their expressions between HCC and non-tumor tissues in TCGA cohort." (PMID 35739471, 2022). "As shown, pathways of PD‐L1, GP1BA, RESISTIN and SPP1 are exclusively activated in tumour." (PMID 39934971, 2025).
cancer (27 papers, 2010 to 2025). A tumor composed of atypical neoplastic, often pleomorphic cells that invade other tissues. "In addition, knockout of receptors on platelets, such as glycoprotein Ib platelet subunit alpha (GPIbα), glycoprotein VI platelet (GPVI), and P-selectin, can reduce cancer cell survival and experimental metastasis 19-22." (PMID 37705745, 2023).
cardiovascular disease (7 papers, 2018 to 2023). "A Kozak variant located in the -5 nucleotide of GP1BA, coding a component of the GP Ib-IX-V receptor complex has been considered a susceptibility factor for the development of cardiovascular disease." (PMID 37344844, 2023).
infection (6 papers, 2010 to 2025). The state of being infected such as from the introduction of a foreign agent such as serum, vaccine, antigenic substance or organism. "In addition, the PI3K-Akt signaling pathway-related genes were expressed at lower levels in SFTSV infection 24 and 48 h, for example, GP1BA, PIK3CA, PIK3CB, AKT3, PRKG1, and PRKG2." (PMID 37211158, 2023). "In addition, genes related to PI3K-Akt signaling pathway showed downregulation and inhibition at 48 h post-infection, such as GP1BA, PIK3CA, AKT3, and PLA2G4A." (PMID 37211158, 2023).
hematological diseases (1 paper, 2022). "However, according to publications and databases, the detected gene variants, except for the GP1BA variant, have not yet been associated with inherited hematological diseases." (PMID 35055070, 2022).
GP1BA also shares sentences with these, for which no sentence is quoted: COVID-19 (9 papers); myocardial infarction (9); melanoma (7); Sepsis (6); immune thrombocytopenia (5); breast cancer (4); coronary heart disease (4); infective endocarditis (4); liver cancer (4); bacterial infection (3); diabetes (3); hepatocellular carcinoma (3); metabolic syndrome (3); Miscarriage (3); thrombotic disease (3); acute coronary syndrome (2); acute myeloid leukaemia (2); anemia (2); brain injury (2); coagulation disorder (2); dengue (2); endocarditis (2); endothelial dysfunction (2); gastric cancer (2); Glanzmann thrombasthenia (2); hemorrhage (2); hepatitis B (2); Hyperglycemia (2); ischemia (2); Lupus (2).
A further 72 diseases each share a sentence with GP1BA in 2 papers or fewer.